TPO (thyroid peroxidase)
Diseases named in the same sentence as TPO in open-access papers (continued):
Sharing a sentence is not in itself a finding about the gene and the disease.
vitiligo (19 papers, 2006 to 2025). Generalized well circumscribed patches of leukoderma that are generally distributed over symmetric body locations and is due to autoimmune destruction of melanocytes. "The present study observed a significant elevation in the mean values of the thyroid antibodies (anti-TG and anti-TPO Abs), suggesting a strong association between AITDs and vitiligo." (PMID 36694854, 2023). "The presence of anti-TPO antibodies was significantly associated with a long duration of vitiligo and a positive family history of vitiligo, and anti-thyroglobulin antibodies were significantly associated with the female gender." (PMID 36556267, 2022). "The intensity of the association of the presence of anti-TPO with vitiligo was 16.2% (Phi & Cramer's V = 0.162)." (PMID 16526964, 2006). "Vitiligo was the most frequent coexisting disease—every case of vitiligo was associated with the presence of thyroid autoantibodies, and ~7.5% of girls with positive anti-TPO or/and anti-TG had vitiligo." (PMID 31417494, 2019). "All but one (96.4%) of the anti-TPO Ab positive participants reported disease activity with a VIDA score “≥1” indicating that anti-TPO Ab positivity could be associated with progressive vitiligo disease activity." (PMID 25653881, 2015). "Our study reported a significant elevation in the mean values of the thyroid antibodies (anti-TG and anti-TPO antibodies) in vitiligo subjects compared to control subjects in this setting." (PMID 36694854, 2023). "There was a statistically significant difference in terms of mean anti-TPO and anti-TG values between the case and control groups in which subjects with vitiligo reported significantly higher values (p < 0.05)." (PMID 36694854, 2023). "A study conducted among 98 vitiligo subjects estimated the prevalence of anti-TPO Ab in 34.7% of disease subjects." (PMID 36694854, 2023). "Our study showed a significant rise in mean anti-TPO and anti-TG antibody levels among vitiligo patients." (PMID 36694854, 2023). "Among 325 vitiligo patients identified, anti-thyroid peroxidase and anti-thyroglobulin were positive in 90 (27.7%) and 63 patients (19.4%), respectively." (PMID 29362715, 2017). "A study regarding 87 vitiligo patients demonstrated positive anti-TG titers in 23% (20/87) of the patients and TPO-Ab were positive in 24.1% (21/87) of the patients, and the results were found significantly higher when compared to healthy controls." (PMID 26355833, 2015). "In vitiligo patients, 9 (8.3%) had elevated anti-TG levels and 16 (14.8%) had elevated anti-TPO, and in 17 patients (15.7%) TSH levels were elevated and 3 (2.8%) patients had elevated fT4 levels and 5 (4.6%) had elevated fT3 levels." (PMID 26355833, 2015). "In the patients with vitiligo, geometric mean of anti-TPO levels was 18.52 (7.94–1000.00) IU/mL and in alopecia patient the mean was found as 18.70 (7.38–1000.00) IU/mL." (PMID 26355833, 2015). "Previous researchers have reported prevalence of anti-TPO antibody positivity in vitiligo patients from around 11% to as much as 50%." (PMID 25653881, 2015). "With regard to the site of onset, while an equal number of participants in the anti-TPO Ab positive group reported an onset of vitiligo in head and neck, trunk, upper limb, and lower limb (25% each), none reported genitals as a site of onset." (PMID 25653881, 2015). "Patients reporting coincident precipitating trigger for vitiligo lesions were more likely to report positive for anti-TPO Ab." (PMID 25653881, 2015). "Betterle showed a significant relationship between anti-TPO Ab with long lasting vitiligo in their patients." (PMID 25653881, 2015). "According to our study the rate of positive anti-TPO was significantly higher in vitiligo patients compared with control subjects." (PMID 16526964, 2006). "Anti-TPO was detected in seventeen cases (18.1%) in vitiligo patients compared with 7 cases (7.3%) in the control group: The difference was statistically significant with a p-value of 0.025." (PMID 16526964, 2006).
vitiligo (continued). "Anti-TPO was detected in 17 (18.1%) of patients affected by vitiligo, while this figure was 7 (7.3%) in the control group; the difference was significant with p-value < 0.025 (Phi & Cramer's V = 0.162)." (PMID 16526964, 2006). "Our objective was to compare the frequency of thyroid peroxidase antibody (anti-TPO) in vitiligo patients with healthy subjects in Iran." (PMID 16526964, 2006). "According to our study, anti-TPO was shown to be significantly more common in vitiligo patients especially in young women, compared with control group." (PMID 16526964, 2006). "Anti TPO and anti TG antibody levels were measured in vitiligo patients and matched controls." (PMID 41623741, 2025). "Physical trauma was the most common trigger of vitiligo in the anti-TPO Ab positive participants." (PMID 25653881, 2015). "While nearly 10% of the participants with anti-TPO Ab positivity had the trichrome variant of vitiligo, the proportion was just 4.2% for their anti-TPO Ab negative counterparts." (PMID 25653881, 2015). "Likewise, 18.5% of vitiligo patients in the age range of 26 to 35 versus 0% of controls showed positive anti-TPO with a significant difference (Fisher's exact test = 0.042) ( Phi & Cramer's V = 0.304)." (PMID 16526964, 2006). "Progressive vitiligo was considered a form of the disease in which new lesions had appeared or pre-existing lesions had spread in the last three months; in another study, subclinical hypothyroidism was detected in 27.8% of patients and high levels of anti-TPO antibodies in 40.3% of patients." (PMID 36556267, 2022). "Similarly around 7% of the participants with anti-TPO Ab positivity had the quadrichrome variant of vitiligo; the proportion was 5.2% for their anti-TPO Ab negative counterparts." (PMID 25653881, 2015). "Anti-thyroid peroxidase antibodies were found in two (no hormonal imbalances; anti-thyroglobulin antibodies negative in all children), hypogammaglobulinemia in three, and vitiligo in one child." (PMID 37131308, 2023). "In our study, a statistically significant history of coincident triggering factor with vitiligo was elicited commonly in those with positive anti-TPO Ab status as compared to those with anti-TPO Ab negative status." (PMID 25653881, 2015). "Vitiligo vulgaris was the commonest type of vitiligo in our study irrespective of anti-TPO Ab status." (PMID 25653881, 2015). "In the anti-TPO Ab negative group, majority had onset of vitiligo in the lower limb (37.5%) followed by head and neck and trunk regions (20.8% each)." (PMID 25653881, 2015). "A history of vitiligo precipitating “trigger” was elicited more commonly with those with anti-TPO Ab as compared to those with anti-TPO Ab negative (P = 0.037)." (PMID 25653881, 2015). "History of vitiligo in the family was reported by 10.7% of our anti-TPO positive patients while it was 13.9% in anti-TPO negative patients." (PMID 25653881, 2015). "The difference of the frequency of anti-TPO was not significant regarding the duration and extent of vitiligo." (PMID 16526964, 2006). "A cohort study including 434 patients aimed to investigate the prevalence of thyroid dysfunction in correlation with anti-TPO antibody titers in patients with NSV (nonsegmental vitiligo) in order to investigate the usefulness of screening tests for thyroid pathologies in patients with vitiligo." (PMID 36556267, 2022). "Approximately 34% of vitiligo patients present high levels of thyroid autoantibodies, including anti-thyroglobulin (ATG) and anti-thyroid peroxidase (TPO), even without evident thyroid dysfunction, which suggests a potential pathogenetic role of these antibodies." (PMID 41157208, 2025).
breast carcinoma (18 papers, 2010 to 2025). "In yet another study, a high level of TPO-directed antibodies has been shown to be associated with a lower risk of breast cancer." (PMID 29513734, 2018). "The authors identified a protective effect of anti-TPO and anti-Tg antibodies for breast cancer in this study and a previous study on the association of benign thyroid diseases and cancer." (PMID 28536577, 2017). "We have also analyzed a possible association of TPO levels and the lymph node status in breast cancer patients." (PMID 28575127, 2017). "Also increased thyroid peroxidase levels have been associated with better prognosis in breast cancers." (PMID 24822141, 2014). "Not only this, the presence of anti-TPO autoantibodies give a significant prognostic advantage for breast cancer." (PMID 30881358, 2019). "The anti-TPO and anti-Tg autoantibodies have been given their roles as potential protective agents against breast carcinoma in hypothyroidism." (PMID 30881358, 2019). "In summary, a promoting role of anti-TSHR antibodies on breast cancer has been shown, while the role of anti-Tg and anti-TPO is unclear." (PMID 28536577, 2017). "In this study, we investigated TPO expression levels in a series of fifty-six breast cancer samples paired with normal (peri-tumoral) tissue and its antigenic activity using a panel of well-characterized murine anti-human TPOAbs." (PMID 28575127, 2017). "We detected lower expression levels of TPO in all breast cancer tissue samples than in matched normal tissue (surgical margins), even though it was previously demonstrated that TPO expression levels are similar in both of these tissues." (PMID 28575127, 2017). "We found that these antibodies bound to TPO in 79% (41 of 52; mAb 18) and 87% (45 of 52; mAb 64) of breast cancer samples, and in 59% (17 of 29; mAb 18) and 63% (19 of 30; mAb 64) of normal breast specimens samples." (PMID 28575127, 2017). "This correlation appears consistent with the finding that anti-TPO-positive breast cancer patients had better survival and longer disease-free intervals." (PMID 28536577, 2017). "To this effect, we have investigated TPO expression levels in fifty-six breast cancer samples and in paired adjacent normal tissue using a panel of well-characterized murine anti-human TPOAbs and human TPOAbs." (PMID 28575127, 2017). "A recent meta-analysis of eight studies reported higher anti-TPO and anti-Tg antibodies as well as higher T3 and T4 levels in breast cancer patients than in controls." (PMID 28536577, 2017). "Several studies demonstrated that the levels of thyroid peroxidase autoantibodies (TPOAbs) are increased in breast carcinoma patients." (PMID 28575127, 2017). "A recent study demonstrated that thyroid peroxidase mRNA and protein are also expressed in breast cancer tissue and in peri-tumoral regions." (PMID 28575127, 2017). "Although the expression of TPO in breast cancer has long been postulated, the presence of TPO in breast cancer tissue has only recently been shown." (PMID 28575127, 2017). "We analyzed TPO protein expression in paired cancer and normal breast surgical samples from twelve breast cancer patients by immunoprecipitation with anti-peptide P14 serum followed by immunoblotting." (PMID 28575127, 2017). "Data regarding a correlation between higher levels of free T4 (FT4) and triiodothyronine, as well as lower levels of thyroid peroxidase autoantibodies (TPO-Ab) and higher breast cancer incidence, are accumulating." (PMID 27648070, 2016). "If compared with the HER-2 antigen in breast cancer, TPO is less expressed in NPA cells, explaining the low levels of complement-, cell-mediated cytotoxicity and anti-proliferative effects we observed." (PMID 20145622, 2010). "Moreover, breast cancer patients have a higher prevalence of thyroid peroxidase autoantibodies, likely due to the co-expression of thyroid peroxidase in both the thyroid and some breast tissues." (PMID 37781188, 2023).
breast carcinoma (continued). "Note, four out of eight TPO isoforms recently related to breast cancer lacked intron 10, where TPO polymorphism is contained." (PMID 32218930, 2020). "Several studies have reported increased levels of TPO antibodies in breast carcinoma patients." (PMID 29513734, 2018). "The putative protective role of TPO autoantibodies in breast cancer could be explained by the fact that peritumoral and cancerous breast tissue express TPO." (PMID 29513734, 2018). "Expression of TPO in breast cancer together with its antigenic activity may have beneficial effects in TPOAb-positive breast cancer patients." (PMID 28575127, 2017). "Thus, we show for the first time that TPO expressed in breast cancer tissue shares immunological characteristics with the thyroid-expressed TPO." (PMID 28575127, 2017). "TPO expression was detected in breast cancer cells and in the adjacent peri-tumoral margins." (PMID 28575127, 2017). "In nearly all examined breast cancer tissue samples, positive TPO immunostaining was observed when three monoclonal antibodies recognizing linear epitopes were used: mAb 47 (positive staining observed in 52 out of 52 exploitable samples), mAb A4 (50 out of 51) and ab76935 (52 out of 52)." (PMID 28575127, 2017). "Additionally, we observed statistically significant decrease in the TPO expression levels in more clinically advanced breast cancer cases, and a decrease in TPO expression in patients with regional lymph node metastasis." (PMID 28575127, 2017). "All antibodies may have a tumor-promoting role in breast cancer carcinogenesis despite anti-thyroid peroxidase antibodies having a positive prognostic effect in patients with overt disease." (PMID 28536577, 2017). "A causative role of chronic inflammation might also be deduced in breast cancer development since anti-TPO antibodies are able to cross-react with lactoperoxidase and initiate the inflammatory process." (PMID 28536577, 2017). "Therefore, the similarities in biochemical and antigenic properties of breast and thyroid TPO may partially explain the protective role of TPO autoantibodies in breast cancer patients and help further elucidate its mechanism." (PMID 29513734, 2018). "Moreover, we detected that TPO transcript levels are lower in more advanced breast cancers." (PMID 28575127, 2017). "Anti-TPO antibodies might initiate chronic inflammation and destruction of mammary cells via cross-reactivity with lactoperoxidase, but generation of oxidative stress by lactoperoxidase activity alone might also promote breast cancer." (PMID 28536577, 2017). "An increased prevalence of melanoma, colon cancer, breast cancer, and hematological malignancies in patients suffering from GD or HT has been identified, but the overall risk for breast, colon, kidney, and uterine cancer was lower in patients with anti-TPO and anti-Tg antibodies than without." (PMID 28536577, 2017). "There are also studies in which no influence of TPO antibodies on breast cancer patients’ outcome was observed." (PMID 29513734, 2018). "Recently, TPO was shown to be present in breast cancer tissue samples but its antigenicity has not been analyzed." (PMID 28575127, 2017).
thrombosis (18 papers, 2010 to 2026). "In patients with primary immune thrombocytopenia (ITP), the risk of thrombosis associated with thrombopoietin receptor agonists (TPO-RAs) remains debated." (PMID 42006039, 2026). "Previous reports in non-SLE ITP populations have described venous and arterial thrombosis during TPO-RA therapy; therefore, clinicians should assess baseline thrombosis risk and monitor patients closely when using these agents in SLE." (PMID 41536373, 2025). "Studies have described a spectrum of thrombotic complications associated with TPO-RA therapy, including pulmonary embolism, deep vein thrombosis, extensive CVST, portal vein thrombosis, ischemic stroke, and myocardial infarction." (PMID 41404254, 2025). "We evaluated the incidence of thrombotic events, given that patients with ITP have an increased incidence of arterial and venous thrombosis, and this risk increases with certain treatments, such as splenectomy and TPO-RA, and even more with COVID-19 infection." (PMID 33804346, 2021). "The studies that reinforce this contribution are scanty; however, in a prior study, we have reported a significant association between TPO and venous thrombosis risk." (PMID 32218930, 2020). "Data from TPO‐RA studies indicate that these agents may be associated with a small additional risk of arterial and venous thrombosis." (PMID 40909397, 2025). "It is unclear whether TPO-RA increases the risk of thrombosis in patients with AA." (PMID 38800784, 2024). "The literature consistently emphasizes the need for close monitoring of platelet levels, adherence to target ranges, and awareness of early symptoms suggestive of thrombosis in patients receiving TPO-RAs." (PMID 41404254, 2025). "Thrombosis should be considered when TPO-RA is administered during the immunosuppressive treatment of AA." (PMID 38800784, 2024). "This gap underscores the need to characterize TPO-RA-induced coronary thrombosis." (PMID 40936593, 2025). "Patients maintained on TPO-RA have had sustained response rates of up to 70% at 6 months, but vein thrombosis rates are increased with these agents, and annualized thrombosis rates appear to be 2–3 times higher in patients treated with TPO-RA than in other ITP patients." (PMID 38999278, 2024). "Therefore, TPO-RA-related venous thrombosis has always been the key concerns for clinicians and may limit the use of TPO-RAs in clinical practice." (PMID 36258065, 2023). "This study compared the thrombosis occurrence in ITP patients before and after the launch of TPO-RAs in China, to explore the relationship between TPO-RAs and thrombosis in ITP patients." (PMID 42006039, 2026). "However, the risk of thrombosis during ITP treatment with TPO-RA is higher than without TPO-RA." (PMID 38800784, 2024). "Although the utilization rate of TPO-RAs increased significantly after 2018, no corresponding significant change in thrombosis incidence was observed." (PMID 42006039, 2026).